ALCAM (activated leukocyte cell adhesion molecule)
Diseases named in the same sentence as ALCAM in open-access papers (continued):
Sharing a sentence is not in itself a finding about the gene and the disease.
prostate carcinoma (continued). "Several studies have looked at ALCAM immunostaining in prostate cancer." (PMID 31695844, 2019). "Significantly higher levels of ALCAM were observed in patients who died of prostate cancer (PRCa) compared to those who were still alive (p < 0.001) and in M1 patients compared to M0 patients (p = 0.002), with borderline significant elevations observed in N1 compared to N0 patients (p = 0.05)." (PMID 31695844, 2019). "The prognostic potential of serum ALCAM was also assessed in 229 prostate cancer patients." (PMID 31695844, 2019). "In summary, our current data suggest that serum ALCAM may have promise as a prognostic indicator in prostate cancer." (PMID 31695844, 2019). "The current study aims to further explore the functional role of ALCAM in regulating aggressive traits in prostate cancer cells and their responsiveness to environmental factors, together with assessing the potential of serum ALCAM as a marker of prostate cancer progression." (PMID 31695844, 2019). "By contrast, high ALCAM is correlated with low-grade less aggressive cases of prostate cancer." (PMID 23024593, 2012). "In addition, a recently described internalizing single-chain antibody, targeting ALCAM has been suggested for the potential intracellular delivery of various therapeutic agents to prostate cancer cells." (PMID 22745698, 2012). "Furthermore, others have found that immunoliposomes coated with a recombinant anti-ALCAM monoclonal antibody were taken up by prostate cancer cell lines expressing this antigen." (PMID 23024593, 2012). "In addition, Sanders et al45 determined the serum ALCAM levels in samples of 239 PC patients and found higher ALCAM levels to be associated with higher Gleason‐score, T‐stage and PSA levels suggesting an association between increasing serum ALCAM concentrations during prostate cancer progression." (PMID 35689436, 2022). "Additionally, elevated serum ALCAM is indicative of progression and poorer patient outlook, and demonstrates comparable prognostic ability to PSA in terms of metastasis and prostate cancer survival." (PMID 31695844, 2019). "Using the TNMplot database, we compared ALCAM gene expressions between normal and tumor tissues in several organs and found ALCAM expression to be significantly elevated in breast, lung, renal, thyroid and prostate cancers compared with corresponding nonmalignant tissues." (PMID 35689436, 2022). "Moreover, ALCAM mediates the resistance of prostate cancer to enzalutamide (ENZA), a second-generation androgen receptor inhibitor frequently used for treating metastatic castration-resistant prostate cancer and ALCAM gene silencing in drug-resistant cells could enhance ENZA sensitivity." (PMID 37701037, 2023).
lung cancer (28 papers, 2013 to 2023). A malignant neoplasm involving the lung. "Again in lung cancer cells, knocking down of ALCAM resulted in a reduction in adhesion to brain endothelial cells both in culture and shear stress conditions." (PMID 34680335, 2021). "Lung cancer cells, after knocking down ALCAM, showed more regular presence in the central ventricle and produced high frequencies of metastatic brain tumours compared to control cells." (PMID 34680335, 2021). "A study by Kinoshita and colleagues showed that soluble ALCAM, in the name of extracellular soil signal sensor receptors (exSSSRs), could suppress the metastasis of lung cancer when it conjugated with a human IgG2-Fc." (PMID 36614319, 2023). "For lung cancer, CD133, CD44, CD90, CD166 (ALCAM), CD177, CD87, ALDH1A1, ABCG2, EpCAM, and CXCR4 have been reported to be lung CSC markers." (PMID 35158999, 2022). "We first studied the A549 lung cancer cell line that expresses the effector LRP6 (7, 341 copy/cell) and the guide ALCAM (874, 813 copy/cell)." (PMID 29335534, 2018). "Subpopulation of nonsmall cell lung cancer (NSCLC) triple-positive for EPCAM, ALCAM, and CD44 possessed CSC characteristics, including being highly proliferative, having greater clonogenicity, ability for self-renewal through spheroid formation, and chemoresistance." (PMID 32085563, 2020). "CD166/ALCAM is a 100–105 kD type I transmembrane glycoprotein member of the immunoglobulin superfamily of proteins, which has also recently been reported as a CSC marker in colorectal and lung cancers." (PMID 23947765, 2013).
ovarian carcinoma (21 papers, 2008 to 2024). A malignant neoplasm originating from the surface ovarian epithelium. "Our study demonstrates the unfavourable prognostic role of MAN1A1 in ovarian cancer, probably caused by an altered ability of spheroid formation, and the strong influence of this glycosylation enzyme on the prognostic impact of ALCAM." (PMID 31659304, 2019). "Our study showed that ALCAM was N-glycosylated in ovarian cancer, and there were two N-glycosylation sites at Asn90 and Asn95." (PMID 36482940, 2022). "Inhibition of the degree of glycosylation of ALCAM by kifunensine results in the shift of ALCAM from the membrane fraction to the cytoplasmic fraction, which also coincides with the increase in cell migration of ovarian cancer cells." (PMID 34680335, 2021). "In patients with ovarian cancer (n = 61), serum levels of ALCAM are higher than controls and significantly correlated with protein marker CA125/MUC16." (PMID 34680335, 2021). "A recent study has shown that ALCAM expression has a connection with the survival of patients with ovarian cancer, and this connection is dependent on the status of a mannosidase MAN1A1 (Mannosidase Alpha Class 1A Member 1)." (PMID 34680335, 2021). "Some of them, such as MUC4, CD44, L1CAM, ALCAM and P-cadherin, promote the malignant tendency of ovarian carcinoma cells." (PMID 30274262, 2018). "Altered expression of several CAMs, such as mucins, integrins, CD44, L1CAM, cadherin, claudins, EpCAM, ALCAM and METCAM/MUC18, is linked to the malignant progression of ovarian carcinoma." (PMID 30274262, 2018). "On the contrary, in breast and ovarian cancer ALCAM cytoplasmic overexpression and low membrane expression were associated with disease progression." (PMID 21364949, 2011). "A similar anti-adhesive activity would be also expected by antibody-mediated blockade of ALCAM adhesive functions, which increased ovarian cancer cells motility in a previous report." (PMID 21364949, 2011). "There is an emerging consensus that low membrane level of ALCAM is a bad prognostic marker in breast and ovarian cancer." (PMID 21364949, 2011). "Decreased/lost ALCAM membrane expression is a marker of poorer outcome in epithelial ovarian cancer." (PMID 19079610, 2008). "Our previous studies suggested that core fucosylation plays important roles in liver cancer proliferation and migration; whether core fucosylation of ALCAM has effect on the ovarian cancer progress could be further explored." (PMID 36482940, 2022). "Indeed, ALCAM is expressed at the cell surface of ovarian cancer cells, and its shedding by ADAM17 is involved in cell migration and invasion." (PMID 36140519, 2022). "Accordingly, ALCAM mediates leukocyte transendothelial migration and trafficking into the central nervous system and the growth, progression and metastasis of many different tumors, including colorectal and ovarian carcinomas." (PMID 35628559, 2022). "Moreover, activation of ADAM17 by EGF increases ALCAM shedding by ovarian cancer cells and in vitro invasiveness." (PMID 36140519, 2022). "Additionally, ALCAM is one of the few mitochondrial proteins highly raised in an ovarian cancer cell line that is resistant to cisplatin (A2780-CP20)." (PMID 34680335, 2021). "Both transmembranous ALCAM and soluble ALCAM in ascites fluid have been investigated as possible tumoral biomarkers and may be indicators of an aggressive phenotype in ovarian cancer." (PMID 33415077, 2020). "In this context, we have previously demonstrated that ALCAM is released from epithelial ovarian cancer (EOC) cells by a metalloprotease-dependent mechanism, leading to the generation of a natural soluble form of ALCAM that contains the greater part of the ectodomain." (PMID 21364949, 2011). "More recently, miR-378 and its downstream targets, ALCAM and EHD1, have been proven to be potential biomarkers of the response to anti-angiogenic therapy in ovarian cancer." (PMID 26242216, 2015).
pancreatic cancer (21 papers, 2009 to 2025). "The overexpression of ALCAM is also an independent prognosis marker for poor survival and early tumor relapse in PDAC, with secreted ALCAM being proposed to be a novel diagnostic marker for pancreatic cancer." (PMID 36009530, 2022). "In pancreatic cancer cells, a reduced ALCAM expression has also been shown to be associated with chemoresistance, in that case to gemcitabine and actinomycin D." (PMID 22475274, 2012). "In addition, increased ALCAM expression was strongly associated with poor prognosis of gastric and pancreatic cancer patients." (PMID 40118855, 2025). "Following showing a positive correlation in the clinical settings, we went to create cell models of gastric and pancreatic cancer cells as well as mesothelial cells with altered levels of ALCAM expression." (PMID 36614319, 2023). "The pancreatic cancer cell line MIA PaCa-2 showed relatively lower ALCAM expression, thus it was used to create ALCAM overexpression cell model." (PMID 36614319, 2023). "ALCAM expression in gastrointestinal cancers, including gastric and pancreatic cancers, has a predictive value in the development of peritoneal metastasis, a detrimental condition for the patients." (PMID 36614319, 2023). "Knocking down ALCAM in gastric or pancreatic cancer cells dramatically reduced the pace of adhesiveness to MET5A mesothelial cells that expressed high levels of ALCAM." (PMID 36614319, 2023). "The present study has reported for the first time that levels of ALCAM in primary gastric cancer and primary pancreatic cancer has a significant value in predicting the likelihood of patients to develop peritoneal metastasis." (PMID 36614319, 2023). "Next, we analyzed if the levels of ALCAM had a relationship with the peritoneal metastasis related survival of patients with gastric and pancreatic cancer." (PMID 36614319, 2023). "One of the highlights of the present study is the finding that patients with high levels of ALCAM in gastric and pancreatic tumours tend to have a high chance of developing peritoneal metastasis." (PMID 36614319, 2023). "In order to investigate the role of ALCAM in pancreatic cancer signaling, an IPA Path Designer (Qiagen) analysis was performed." (PMID 36009530, 2022). "Pathway prediction analysis prognosticates that ALCAM has a major role to play in the activation of all major pancreatic cancer-related signaling pathways, making it an important protein to be investigated in CTC panels." (PMID 36009530, 2022). "Another early study involving 97 patients with pancreatic cancer showed that patients who died of pancreatic cancer tend to have stronger ALCAM staining." (PMID 34680335, 2021). "In pancreatic cancer cells, reduction in ALCAM by RNAi has been shown to confer resistance to chemoagents." (PMID 34680335, 2021). "In patients with pancreatic cancer (n = 115), the levels of circulating (soluble) ALCAM were found to be significantly higher than those with chronic pancreatitis and than the control individuals." (PMID 34680335, 2021). "The serum levels of s-ALCAM have been investigated in pancreatic cancer before, but this study was the first to analyze both ALCAM expression and s-ALCAM levels in the same patients." (PMID 22745698, 2012). "In this study, paraffin-embedded samples of 97 patients with pancreatic cancer undergoing potentially curative resection were immunostained against ALCAM, ADAM17 and CK19." (PMID 19603023, 2009). "Our study for the first time shows that the increased cytoplasmic expression of ALCAM is an independent prognostic marker for early tumour relapse and poor OS in pancreatic cancer." (PMID 19603023, 2009). "The differential cellular distribution of ALCAM between pancreatic cancer and corresponding normal pancreatic tissue was highly significant (P=0.0001)." (PMID 19603023, 2009). "Here, we show that overexpression of ALCAM is an adverse prognostic factor for recurrence-free and overall survival (OS) in pancreatic cancer." (PMID 19603023, 2009).
pancreatic cancer (continued). "To obtain some deeper insight in the last mentioned question, we examined a potential co-expression of ADAM17 and ALCAM in pancreatic cancer." (PMID 19603023, 2009). "In the present study, we first explored if expression levels of ALCAM may have an impact on the peritoneal metastases of the patients with gastric and pancreatic cancers." (PMID 36614319, 2023). "Likewise, levels of ALCAM in both human gastric and pancreatic cancer cells were also a determining factor for their adhesiveness to mesothelial cells, a process that was likely to be triggered the phosphorylation of the SRC kinase." (PMID 36614319, 2023). "This clinical evidence supports the critical role of ALCAM in gastric/pancreatic cancer metastasis." (PMID 36614319, 2023). "In a cohort study of pancreatic cancer cases, patients with higher levels of ALCAM was found to have significantly shorter overall survival, and pancreatic cancer tissues had significantly higher levels of ALCAM transcripts than normal pancreas tissues." (PMID 36614319, 2023). "ALCAM is an indicator of peritoneal metastasis in both gastric and pancreatic cancer patients." (PMID 36614319, 2023). "Moreover, RNAi-mediated silencing of ALCAM induced chemotherapy resistance in pancreatic cancer cells." (PMID 26887050, 2016). "ALCAM silencing has been shown to induce chemoresistance in pancreatic cancer cells in vitro." (PMID 22475274, 2012). "Thus, to answer to what extent the proteolytic sheddase of ALCAM by ADAM17 is a relevant step for tumour progression in pancreatic cancer, further experimental studies are required." (PMID 19603023, 2009). "The aim of our study was to evaluate the prognostic significance of ALCAM in pancreatic cancer." (PMID 19603023, 2009). "Thus, we intended to assess a co-expression between ADAM17/TACE and ALCAM in pancreatic cancer and to evaluate a potential co-function." (PMID 19603023, 2009). "Our findings support the hypothesis that the disruption of ALCAM-mediated adhesiveness is a relevant step in pancreatic cancer progression." (PMID 19603023, 2009). "In pancreatic cancer, 56 samples were ALCAM-positive, 41 samples were ALCAM-negative." (PMID 19603023, 2009). "Moreover, ALCAM overexpression is a relevant independent prognostic marker for poor survival and early tumour relapse in pancreatic cancer." (PMID 19603023, 2009). "In analogy, one can speculate that the accumulation of ALCAM in pancreatic tumour cells leads to similar tumour-promoting effects, therefore having a negative prognostic impact." (PMID 19603023, 2009). "We could show that in normal pancreatic tissue, ALCAM is predominantly expressed at the cellular membrane, whereas in pancreatic tumour cells, it is mainly localised in the cytoplasm." (PMID 19603023, 2009). "The findings presented here argue that ALCAM may function as both a ‘seed’ receptor (residing on gastric and pancreatic cancer cells) and a ‘soil’ receptor (residing on the receiving mesothelial cells) during the process of cancer cell seeding in the peritoneal cavity." (PMID 36614319, 2023). "Similarly, it has been shown that only 12% of pancreatic tumours stained positive for ALCAM." (PMID 34680335, 2021). "Gastric cancer cell lines HGC-27 and AGS, pancreatic cancer cell line PANC-1 and mesothelial cell line MET5A were used to generate ALCAM knockdown cell models because of their relatively higher ALCAM expression." (PMID 36614319, 2023). "We created several cell models including MET5A mesothelial cells with ALCAM knockdown, AGS and HGC27 gastric cancer cells with ALCAM knockdown, PANC-1 pancreatic cancer cells with ALCAM knockdown and MIA PaCa-2 cells with ALCAM overexpression." (PMID 36614319, 2023). "Knocking down ALCAM from both the mesothelial cell MET5A and pancreatic cancer cell PANC-1 rendered a marked reduction of cell adhesion, similar to that seen with gastric cancer cells." (PMID 36614319, 2023).
pancreatic cancer (continued). "ALCAM knockdown of the mesothelial cell line MET5A rendered the cells with reduced interaction with both gastric cancer cells and pancreatic cancer cells." (PMID 36614319, 2023). "This suggests that further investigations should be conducted into how other adhesion molecule family members such as ALCAM and NCAM relate to EMT and stem cancer cells in pancreatic cancer." (PMID 33928036, 2021). "In analogy to ALCAM expression, we evaluated immunhistochemical staining of ADAM17 expression in pancreatic cancer." (PMID 19603023, 2009). "Gastric cancer and pancreatic cancer tissues with or without peritoneal metastasis were compared for their levels of ALCAM expression." (PMID 36614319, 2023). "Patients who had peritoneal metastases had significantly higher levels of ALCAM than those without (p = 0.037 for gastric cancer and p = 0.01 for pancreatic cancer)." (PMID 36614319, 2023). "Both gastric and pancreatic tumour tissues from patients who developed peritoneal metastases had higher levels of ALCAM transcript than those without." (PMID 36614319, 2023). "Fujiwara went ahead to show that pancreatic cancer cells with negative/low ALCAM tend to be highly invasive and more tumorigenic in vivo." (PMID 34680335, 2021). "In pancreatic carcinoma, selective transmigration of Tregs involved the mucosal adressin cell adhesion molecule-1 (MAdCAM-1), VCAM-1, E-selectin, and activated leukocyte cell adhesion molecule (ALCAM, also known as CD166)." (PMID 33262763, 2020). "Although the expression of ALCAM is a valuable prognostic and predictive marker in several types of epithelial tumours, its role as a prognostic marker in pancreatic cancer has not yet been reported." (PMID 19603023, 2009). "Overexpression of ADAM17 in pancreatic cancer, however, failed to be a significant prognostic marker and was not coexpressed with ALCAM." (PMID 19603023, 2009). "However, despite its important role in tumour invasion and progression in pancreatic cancer and other types of tumours, immunohistochemical expression of ADAM17 correlates significantly neither with clinical and pathological data nor with ALCAM expression in pancreatic cancer." (PMID 19603023, 2009). "Pancreatic cancer cell lines with high (HPAF) and no (MiaPaCa) ALCAM expression were used as controls." (PMID 23024593, 2012). "This study was conducted to evaluate the expression of the activated leukocyte cell adhesion molecule (ALCAM) in pancreatic cancer (PAC) and to determine whether or not the ectodomain shedding of ALCAM (s-ALCAM) could serve as a biomarker in the peripheral blood of PAC patients." (PMID 22745698, 2012).